BRCA2 (BRCA2 DNA repair associated)
Diseases named in the same sentence as BRCA2 in open-access papers (continued):
Sharing a sentence is not in itself a finding about the gene and the disease.
breast cancer (continued). "BRCA2 significantly positively correlated in T-47D (Pearson r = 0.9366, p<0.0059) breast cancer cells and BRCA1 & p16 negatively correlated but not significant." (PMID 38711004, 2024). "When we analyzed the copy number variations of RNH1 in patient samples from 2 breast cancer TCGA data sets (TCGA, Cell and Firehose Legacy), we found the copy number amplification was significantly higher in BRCA2-low; MLH1-low human breast cancer samples compared with unaltered controls." (PMID 38271119, 2024). "Noticeably, all studies, except for one longitudinal report, analyzed breast cancer risk following HRT in BRCA1 carriers together with no differentiation between BRCA1/2 and BRCA2." (PMID 39201170, 2024). "In contrast, BRCA2-related breast cancer is often ER-positive and, apart from the more frequent contralateral appearance, does not substantially differ from sporadic breast cancer." (PMID 38892081, 2024). "While mammography detects calcifications in BRCA2-related breast cancer, reports indicate a lack of calcifications in BRCA1-related breast cancer." (PMID 39174799, 2024). "Metcalfe et al25 reported a 10-year risk of contralateral breast cancer of 43.4% for BRCA1 carriers and 34.6% for BRCA2 carriers who did not undergo oophorectomy or take tamoxifen." (PMID 38916888, 2024). "A total of 12 patients (14.6%) remained alive with active disease, while 10 patients (12.2%) had succumbed to breast cancer, 6 of whom presented advanced stages (IIIB, n = 4; IIIC, n = 1; IV, n = 1), and most carried PVs in the BRCA1 (n = 4; 40.0%) and BRCA2 (n = 3; 30.0%) genes." (PMID 38893140, 2024). "Individuals with a pathogenic variant in BRCA1, BRCA2, or PALB2 had a risk of breast cancer well above 20% at age 70, regardless of their PRS or family history." (PMID 39669587, 2024). "Nevertheless, when analyzed separately, there was a decrease in both high-grade serous cancer and breast cancer mortalities in BRCA1 mutation carriers, but not in BRCA2 mutation carriers." (PMID 38717180, 2024). "BOADICEA V5’s newest version includes the effects of pathogenic variants (PVs), not restricted to BRCA1 and BRCA2 genes but also in PALB2, CHEK2, ATM, and BARD1 for the breast cancer model and RAD51D, RAD51C, and BRIP1 for the ovarian cancer model." (PMID 39590369, 2024). "Of 491 breast cancer patients with P/LP variants in breast cancer susceptibility genes, 72.3% (n = 355) were BRCA1 or BRCA2 variants, while 139 patients had non-BRCA variants." (PMID 38355628, 2024). "Oophorectomy has been shown to diminish breast cancer mortality in carriers of BRCA1, BRCA2 and CHEK2 mutation mutations but has not yet been studied in breast cancer patients with ATM mutations." (PMID 39543654, 2024). "However, when incorporating the bulk RNA-seq dataset GSE202203 with an additional 3,207 breast cancer samples, the distribution fitting reveals that BRCA1 still follows a log-normal distribution, while BRCA2 shifts to a genextreme distribution." (PMID 39541191, 2024). "This individual had no documented family history of breast cancer, history of hormone treatments, BRCA1, BRCA2, PALB2 or CHEK2 P/LP variants or other explanation on chart review." (PMID 39802765, 2024). "Tumors with an impaired ability to repair DNA double-strand breaks by homologous recombination, including those with alterations in breast cancer 1 and 2 (BRCA1 and BRCA2) genes, are very sensitive to blocking DNA single-strand repair by inhibition of the poly (ADP-ribose) polymerase (PARP) enzyme." (PMID 39351435, 2024). "We found that the risk for skin cancer was increased after a diagnosis of breast cancer for BRCA1 mutation carriers (HR = 1.77, 95% CI: 1.26–2.50, p = 0.001) but not for BRCA2 mutation carriers (HR = 1.13, 95% CI: 0.76–1.67, p = 0.56)." (PMID 38741145, 2024).
breast cancer (continued). "Using the Breast CFR, we found strong evidence that OC use was associated with a substantial (4.5‐fold; p = 0.0001) protective association against breast cancer diagnosed before age 40 for BRCA1 carriers, but not for BRCA2 carriers or noncarriers." (PMID 38504141, 2024). "Q2: Women with breast cancer and a strong family history should perform BRCA1/BRCA2 testing." (PMID 39446329, 2024). "A large prospective cohort study published in 2020, including 2272 BRCA1 and 1605 BRCA2 pathogenic variant carriers, did not observe a protective effect of RRBSO regarding breast cancer in BRCA1 mutation carriers." (PMID 38892081, 2024). "Around that time, the breast cancer genes BRCA1 and BRCA2 had just been cloned, through large transnational collaborations led by Mary-Claire King and Michael Stratton, to identify the genetic defect in women with a high risk of developing familial breast and ovarian cancer." (PMID 39711301, 2024). "Patients with breast cancer carrying BRCA1 and BRCA2 genetic alterations show poor prognoses." (PMID 36865806, 2023). "There was a suggestion for increased premenopausal breast cancer risk for taller BRCA1 and BRCA2 variant carriers, but the association was not significant (HR 1.19 per 10 cm increase, 95% CI 0.91–1.56 and HR 1.32, 95% CI 0.92–1.90, respectively)." (PMID 37340476, 2023). "HR estimates for young-adult BMI (continuous measure) were less than 1 for premenopausal breast cancer risk in both BRCA1 and BRCA2 variant carriers, although the associations were not statistically significant." (PMID 37340476, 2023). "Neither synchronous nor metachronous breast cancer is associated with strong genetic determinants, and only 5% of patients with BBC carry BRCA1 or BRCA2 mutations." (PMID 36879128, 2023). "For 1605 BRCA2 GPV carriers, RRSO carried out before or after age 45 did not decrease breast cancer risk (HRbefore 45 years: 1.07, 95% CI: 0.69–1.64, HRafter age 45: 0.68, 95% CI: 0.40–1.15), followed-up for a mean of 4.9 years." (PMID 37046756, 2023). "RRSO did not decrease breast cancer risk overall (HR: 1.23, 95% CI: 0.85–1.78), or for BRCA1 (HR 1.29: 95% CI: 0.81–2.05) or BRCA2 GPV separately (HR: 1.13, 95% CI: 0.62–2.06)." (PMID 37046756, 2023). "Furthermore, having a family member with breast cancer can increase the chance of developing prostate cancer due to their genetic makeup (e.g., BRCA1, BRCA2, HOXB13, CHEK2, HOXB13 and ATM)." (PMID 37893854, 2023). "In this cohort of 1312 women with a BRCA1/2 GPV, after RRSO the breast cancer risk did not decrease for both BRCA1 (HR: 1.29, 95% CI: 0.81–2.05) and BRCA2 GPV carriers (HR: 1.13, 95% CI: 0.62–2.06) compared to pre-RRSO." (PMID 37046756, 2023). "Familial breast cancer is in most cases unexplained due to the lack of identifiable pathogenic variants in the BRCA1 and BRCA2 genes." (PMID 37316882, 2023). "For ER+ cancer, breast cancer-specific 15-year survival was 49.7%, 55.2%, and 74.7%, among BRCA2-carriers, young and older non-carriers, respectively, whereas for ER-negative cancer, survival was similar (64.0–69.3%) for all three groups." (PMID 38036573, 2023).
breast cancer (continued). "We compared breast cancer-specific survival, effects of ER status, other clinical parameters, and treatment, between three mutually exclusive groups: BRCA2-carriers, non-carriers diagnosed 40 years or younger, and older non-carriers." (PMID 38036573, 2023). "In a group of patients with hereditary breast cancer, PIK3CA mutations were associated with BRCA2 but not BRCA1 mutations, and with luminal-type breast cancer." (PMID 37803017, 2023). "In patients who are found not to carry a founder mutation, we perform full sequencing using gene panels including BRCA1, BRCA2, CHEK2, and PALB2 in breast cancer cases with familial clustering of this cancer and/or in patients with early onset disease (diagnosed at age 45 or below)." (PMID 37510234, 2023). "While early age at diagnosis was strongly associated with BRCA1 and modestly with BRCA2, it was associated with only a very modestly (ATM and CHEK2) or no (PALB2) increased risk of carrying a PV in non-BRCA1/2 breast cancer-associated genes." (PMID 37084156, 2023). "The difference in the association between BRCA1 and BRCA2 carriers may be explained by the difference in proportions of estrogen receptor (ER)-positive breast cancer (22% for BRCA1, 77% for BRCA2)." (PMID 37340476, 2023). "We propose that all women of Orcadian ancestry (worldwide) with a diagnosis of breast cancer should be offered a targeted test for this variant, if a BRCA1/BRCA2 gene screen is not offered as part of their clinical care." (PMID 36927983, 2023). "In contrast, the luminal subtype is a common subtype of breast cancer in BRCA2 mutation carriers, which has a similar frequency to non-BRCA breast cancers." (PMID 36905492, 2023). "The same study found that among women aged <35 years diagnosed with breast cancer and no family history, 9.4% (7.1% for BRCA1 and 4.9% for BRCA2) were carriers of germline mutations." (PMID 36980802, 2023). "Unaffected women with familial breast cancer were about 2-times more likely to carry a PV in one of the high-penetrance breast cancer-risk genes (BRCA1, BRCA2, PALB2) compared to those with no familial breast cancer." (PMID 37084156, 2023). "The most frequent BRCA2 variant in this sample was the previously considered VUS c.122C>T, although carriers with cancer did not report breast cancer." (PMID 37306523, 2023). "This challenges clinical genetic counselling of families with a strong history of breast cancer without identified germline mutations in BRCA1 and BRCA2 (hereafter referred to as non-BRCA1/BRCA2 high-risk families)." (PMID 37316882, 2023). "iNOS/NOS2 axis promotes breast cancer progression through regulating HER2, BRCA1, and BRCA2." (PMID 37795447, 2023). "In exploratory analyses in BRCA1 or BRCA2 mutation carriers, there was little evidence of association of E354Q with breast cancer risk (BRCA1:OR 1.00, 95% CI:0.96–1.05, p = 0.98; BRCA2:OR:1.04, 95% CI:0.98–1.11, p = 0.16)." (PMID 37250804, 2023). "Poly(adenosine diphosphate-ribose) polymerase inhibitors (PARPi) improve progression free survival among patients with HER2 negative (HER2-ve) advanced breast cancer (ABC) and a BRCA1 or BRCA2 mutation compared to chemotherapy (CT)." (PMID 38414929, 2023). "BC occurs mainly due to somatic, genetic, and epigenetic alterations in a lifetime (i.e., non-hereditary), while only 5%–10% of BC cases are hereditary [majority detected with mutations in two tumor-suppressor genes: breast cancer gene 1 (BRCA1) and breast cancer gene 2 (BRCA2)]." (PMID 38090567, 2023). "The authors found a significant reduction in ovarian cancer risk and no increase in breast cancer risk for both BRCA1 and BRCA2 carriers." (PMID 35884518, 2022). "We hypothesize that there are some cross-talk signaling pathways between iNOS expression and the expression of breast cancer protooncogenes: HER2, BRCA1, and BRCA2." (PMID 35740092, 2022).
breast cancer (continued). "Pathogenic germline mutations in the BRCA1 and BRCA2 (BRCA1/2) genes contribute to hereditary breast and ovarian cancer in white/mestizo Colombian women, but there is virtually no genetic data on breast cancer in Colombians of African descent." (PMID 35641219, 2022). "BRCA1 and BRCA2 are potential biomarkers for HRD in ovarian and breast cancer." (PMID 35785170, 2022). "The combined BRCA1 and BRCA2 VUS rate in a cohort of 21,216 Chinese breast cancer cohort was 9.8%." (PMID 35641994, 2022). "PTEN, BRCA1, BRCA2, PI3K, and CCND1 genes were involved with the breast cancer signaling pathway." (PMID 36341349, 2022). "Mutations in BRCA1 and BRCA2, in addition to ERBB2, were also newly present in brain metastatic tumors and not detected in primary breast tumors in eight out of 22 breast cancer patients." (PMID 36507516, 2022). "Paradoxically, in BRCA1 and BRCA2 breast cancer tumors it seems that pCR does not serve as a surrogate marker of better clinical outcome and a higher pCR does not translate into improved disease-free and overall survival." (PMID 36580360, 2022). "But the elevated risk for PC was also noted in patients with breast cancer with a negative test for BRCA1 and BRCA2 mutations." (PMID 35761384, 2022). "Survival time for breast cancer patients did not have a significant association with ER status (p = 0.16), age at diagnosis (p = 0.47), BRCA1 vs. BRCA2 germline mutation (p = 0.4), tumor stage at diagnosis (p > 0.74), or patient recurrence status (p = 0.58)." (PMID 36344544, 2022). "Breast cancer gene-1 (BRCA1) and breast cancer gene-2 (BRCA2) are players in the HRR machinery." (PMID 36230726, 2022). "Along this line, CtIP germline variants have been recently identified in Danish cohorts of breast cancer patients negative for pathogenic mutations of BRCA1 and BRCA2." (PMID 35203293, 2022). "Using the breast cancer study as an example, it was found that the known eight famous genes—BRCA1, BRCA2, PALB2, BARD1, RAD51C, RAD51D, and ATM—in breast cancer research and practice actually lead to very low accuracy in predicting breast cancer status at the stage of diagnosis." (PMID 36298522, 2022). "Of interest is that in southwestern Finland breast cancer onset was similar between BRCA2 families and in non-BRCA families and other counselled families." (PMID 35469032, 2022). "Breast cancer occurs in many genetic factors, such as BRCA1/BRCA2 abnormalities." (PMID 36473847, 2022). "Although the details remain unclear, the breast cancer suppressors BRCA1 and BRCA2 have been suggested to be involved in pathways that prevent R-loop accumulation." (PMID 36229463, 2022). "In our study, we assumed that RRBSO does not reduce the risk of contralateral breast cancer in carriers of the BRCA1 and BRCA2 pathogenic variants." (PMID 36580360, 2022). "Whereas most other women described breast cancer as more manageable due to being readily identifiable through screening or self-examination and “unlikely to kill me” (Elise, 55 years, BRCA2)." (PMID 35887609, 2022). "Because most BRCA1 cases of breast cancer are ER- and most BRCA2 cases are ER+, the frequency of ER+ tumors among the overall BRCA breast cancer patients depends on the relative contribution of the gBRCA2 incidence in unselected breast cancer patients." (PMID 35805038, 2022). "At present, the risk estimates given to women by most healthcare professionals are broad (e.g., 35–85% lifetime risk of breast cancer for BRCA1 and BRCA2) and are not personalised." (PMID 35681696, 2022). "The potential risk of IVF treatment in the setting of germline mutations, such as breast cancer gene (BRCA1 and BRCA2), was not analysed, however the evidence suggests that IVF is safe in patients with such mutations." (PMID 35143625, 2022). "Breast cancer has similar BRCA1 and BRCA2 prevalence at 4.0 and 4.8%, respectively." (PMID 34979999, 2022).
breast cancer (continued). "WES on 290 BRCA1/BRCA2-negative Singaporeans with early-onset breast cancer and/or a family history of breast cancer was done." (PMID 36424660, 2022). "A total of 3.6% of patients carried a pathogenic/likely pathogenic variant in a known breast cancer susceptibility gene: 1.2% in BRCA1, 0.6% in each of BRCA2, ATM, CHEK2 and PALB, none of whom had any family history of breast cancer." (PMID 35039564, 2022). "The frequency of somatic BRCA1 and BRCA2 PV may be between 1 and 3% of patients in unselected breast cancer populations, including ER+/HER2- breast cancer patients and even higher in patients with ER+/HER2- mBC." (PMID 35158866, 2022). "Here, we report the largest WES study on germline DNA from Asian breast cancer patients who had undergone cancer risk assessment and were BRCA1 and BRCA2 mutation-negative." (PMID 36424660, 2022). "If BRCA1 or BRCA2 is damaged by a BRCA mutation, damaged DNA is not repaired properly, and this increases the risk for breast cancer." (PMID 35837379, 2022). "This is further reflected by several preclinical studies showing that BRCA2-mutated, but not BRCA1-mutated breast cancers, are responsive to treatment with ICIs." (PMID 36077694, 2022). "Reversion mutations within multiple genes in the HRR pathway, including BRCA1, BRCA2, RAD51C, RAD51D, and PALB2, have been reported in ovarian, prostate, and breast carcinomas as a mechanism of acquired or primary resistance to platinum-based chemotherapy and PARP inhibitors 7-18." (PMID 35281878, 2022). "The nearly identical timing of the “first wave” of mammary tumor development suggests that BRCA1, BRCA2, and PALB2 may be functionally equivalent in mammary tumor suppression." (PMID 33893322, 2021). "The cumulative risk of breast cancer was higher in both BRCA1 and BRCA2 male heterozygotes compared to those without a BRCA1/2 pathogenic variant at all ages." (PMID 33959510, 2021). "In breast cancers, most of the studies have reported worse clinical prognosis for patients with BRCA1 mutations compared with BRCA2 mutation carriers and non-carriers." (PMID 33525353, 2021). "The enrichment for breast cancer in non-Roma is due to variants with increased allele frequencies in ATM, BRCA2, and NQO2 genes." (PMID 34220960, 2021). "BRCA2 K3326X was assessed in a case control study of 2634 breast cancer cases from familial cancer clinics and 1996 non-cancer population controls." (PMID 33503928, 2021). "The 10-year cumulative risk of contralateral breast cancer is 5.1% for non-carriers, 21.1% for patients with BRCA1 mutation, and 10.2% for BRCA2 mutations." (PMID 33996049, 2021). "Indeed much of the initial observations on PCa heritability arose via a circuitous route from breast cancer studies examining BRCA1 and BRCA2." (PMID 34830851, 2021). "This study assesses the role of VDR and GC SNPs on breast cancer (BC) recurrence and survival in a cohort of patients with a family history of breast cancer, without the pathogenic variant for BRCA1 and BRCA2." (PMID 33917614, 2021). "Moreover, based on the sequencing genomic DNA (from 1,370 cases and 1,635 controls), approximately 5.6% of patients are the carriers of a pathogenic variant in breast cancer gene 1 (BRCA1), BRCA2, partner and localizer of BRCA2 (PALB2), or tumor protein 53 which are the main penetrant genes of BC." (PMID 36046117, 2021). "Analysis of all BRCA1/2 cases showed no reduction in the risk of developing breast cancer in the RRSO-treated group, although the BRCA2 mutation-bearing group showed an 83% reduction in risk at < 50 years of age." (PMID 32862296, 2021).